EGFR (epidermal growth factor receptor)
Diseases named in the same sentence as EGFR in open-access papers (continued):
Sharing a sentence is not in itself a finding about the gene and the disease.
non-small cell lung carcinoma (continued). "A study revealed that pembrolizumab monotherapy has shown significant improvements in overall survival as a first-line treatment compared with conventional chemotherapy for locally advanced or metastatic non-small-cell lung cancer without sensitising EGFR or ALK alterations when PDL1 TPS ≥ 1%." (PMID 32587640, 2020). "Non-small cell lung cancer (NSCLC) patients treated with erlotinib, an EGFR-TKI, show altered differentiation of the pilosebaceous epithelium as the primary process of EGFR inhibition in the human skin and is hypothesized as a trigger of inflammation and skin rash." (PMID 31703435, 2019). "In December 2018, atezolizumab in combination with bevacizumab and standard chemotherapy for the first-line treatment of patients with metastatic non-squamous, non-small cell lung cancer (NSq NSCLC) with no EGFR or ALK genomic tumor aberrations was approved by the FDA." (PMID 31488176, 2019). "miR-7-5p is more of a tumor suppressor that represses oncogenic proteins such as EGFR, IGF1R, IRS-1, IRS-2, RAF1, PIK3CD, mTOR, and PI3K, in various cancers including PDAC, liver, breast, non-small cell lung carcinoma (NSCLC), colorectal (CRC) and ovarian." (PMID 31510100, 2019). "Predictive biomarkers of tumor response to EGFR inhibitors have been well established in non-small cell lung cancer (NSCLC) and colorectal cancer (CRC) but these mechanisms (including EGFR and KRAS mutations) are extremely rare and are not clinically relevant to HNSCC." (PMID 31346466, 2019). "This is particularly evident in non-small-cell lung cancer (NSCLC) patients, where in approximately 30% of patients a tissue sample is not available for epidermal growth factor receptor (EGFR) mutation analysis, either at diagnosis or as the disease progresses." (PMID 30092778, 2018). "Importantly, in non-small-cell lung carcinoma (NSCLC) tumor xenografts, the expression of a EGFR-dependent tyrosine phosphorylation mimetic BECN1 mutant resulted in reduced autophagy activity, increase of tumor growth, and resistance to TKI (tyrosine kinase inhibitor) therapy." (PMID 30572663, 2018). "Targeting the receptor for epidermal growth factor receptor (EGFR) has been rewarding in cancer and many pharmaceuticals are approved alone or in combination with chemotherapy for colorectal cancer, non-small-cell lung cancer, and pancreatic cancer, among others, but not for gliomas." (PMID 30619758, 2018). "A survival analysis and the influencing factors for non-small cell lung cancer (NSCLC) patients with brain metastases accepting first-generation epidermal growth factor receptor tyrosine kinase inhibitor (EGFR-TKIs) treatment have not yet been elucidated to date." (PMID 28228223, 2017). "Afatinib, a covalent inhibitor of the epidermal growth factor receptors (EGFR), was approved by the FDA for the treatment of EGFR-driven non-small cell lung carcinoma (NSCLC) in 2013." (PMID 27551330, 2016). "In Australia, EGFR molecular testing is subsidied for testing of tumour tissue from a patient diagnosed with non-small cell lung cancer, shown to have non-squamous histology or histology not otherwise specified to determine EGFR gene status for access to erlotinib or gefitinib." (PMID 26101870, 2015). "In comparison with chemotherapy, EGFR-tyrosine kinase inhibitors (TKI), including gefitinib, erlotinib and afatinib, have provided a better outcome and quality of life for patients with advanced EGFR-mutant non-small cell lung cancer (NSCLC) and have become one of the standard first line therapies." (PMID 25789627, 2015). "Because of the promising results of EGFR inhibitors in animal models of HCC and their efficacy in other solid human tumors such as non-small cell lung carcinomas and colorectal cancers, it was hypothesized that targeting the EGFR signaling pathway might be beneficial also in HCC." (PMID 26729094, 2015).
non-small cell lung carcinoma (continued). "Not only in front line but also in subsequent therapy, EGFR-tyrosine kinase inhibitors (TKIs) in comparison with chemotherapy have demonstrated significantly higher response rate and longer progression-free survival (PFS) in patients with EGFR-mutant non-small cell lung cancer (NSCLC)." (PMID 25215536, 2014). "It has been proven that chemotherapy combined with epidermal growth factor receptor-tyrosine kinase inhibitors (EGFR-TKIs) could not increase response for advanced non-small cell lung cancer (NSCLC), but its cellular mechanism was not well known." (PMID 21569641, 2011). "EGFR targeting with TKIs, such as gefitinib and erlotinib, has proven successful in molecularly defined subsets of patients with non-small cell lung cancer (NSCLC), where specific mutations of the EGFR tyrosine kinase domain, but not protein expression, were predictive of the clinical efficacy." (PMID 21266046, 2011). "Work on the response of non-small-cell lung cancer (NSCLC) to anti-EGFR therapies suggests that EGFR expression detected by immunohistochemistry (IHC) is not the best indicator of tumour-cell dependence on EGFR." (PMID 22192147, 2011). "For example, the FDA has approved two monoclonal antibodies (cetuximab and panitumumab), which target EGFR, for treatment of patients with metastatic CRC and two EGFR tyrosine kinase inhibitors (gefitinib and erlotinib) for treatment of patients with metastatic non-small cell lung cancer." (PMID 24213116, 2011). "However, in line with experience from colorectal cancer and non-small-cell-lung cancer (NSCLC), it may be important for prediction of response to EGFR-targeted therapies." (PMID 19358724, 2009). "Furthermore, EGFR TKIs have the capacity to reduce hypercalcaemia in two lung SCC models, and their use to treat various types of non-small cell lung cancer may prevent the development of HHM." (PMID 17533397, 2007). "Clinical trials using EGFR inhibitors such as Cetuximab (IMC-C225) have shown encouraging activity both as a monotherapy as well as in combination with either chemotherapy or radiation, including patients with head and neck squamous cell carcinoma, non-small-cell lung cancer and colorectal cancer." (PMID 16570047, 2006). "Although clinical experience with combined VEGF/EGFR inhibition is limited, in a recent phase I/II trial of patients with previously treated non-small-cell lung cancer (NSCLC; nonsquamous histology) the combination of erlotinib and bevacizumab showed encouraging antitumour activity." (PMID 15928653, 2005). "Similarly, in non-small cell lung cancer, the overabundance of TRIP13 intensifies resistance to gefitinib through the manipulation of autophagy processes and the alteration of phosphorylation within the epidermal growth factor receptor (EGFR) signaling pathway." (PMID 41007830, 2025). "However, studies in other cancers known to be impacted by EGFR alterations, particularly colon cancers and non-small cell lung carcinoma of the lung, have shown clinical indication for EGFR targeted therapy even in cases where all tumor cells do not express the mutation." (PMID 41212363, 2025). "Specifically, the product of KIF5B-RET activated multiple RTKs, including EGFR, providing vulnerabilities that could be targeted using combinations such as sorafenib with erlotinib or paclitaxel as potential treatment options for KIF5B-RET-positive non-small cell lung cancer (NSCLC)." (PMID 39722550, 2025). "The oncogenic variant of the epidermal growth factor receptor, known as EGFRvIII, is not present in normal tissue but is exclusively expressed in tumors of several cancer types, including glioblastoma (GBM), breast cancer, and non-small cell lung cancer (NSCLC)." (PMID 37958672, 2023).
non-small cell lung carcinoma (continued). "Also, the FDA in 2021 approved the combined treatment of tiragulumab with atezolizumab as the first-line treatment for patients with non-small cell lung cancer (NSCLC) malignancy and tumor cells with high expression of PD-L1 without mutations in the tumor gene EGFR." (PMID 36276117, 2022). "In addition, gefitinib sensitivity was also restored in non-small cell lung cancer cells when FGF2 and FGFR1 were inhibited via siRNA and treatment with a small molecule inhibitor, PD173074, suggesting FGFR activation as a potential mechanism of acquired resistance to EGFR-TKs." (PMID 34830836, 2021). "In patients of advanced non-small-cell lung cancer (NSCLC) with tissue epidermal growth factor receptor (EGFR) T790M-positive, an absence of detectable plasma T790M at baseline is associated with longer progression-free survival, which may be attributed to a lower disease burden." (PMID 34203201, 2021). "Indeed, Pan-HER induced downmodulation of its targets EGFR and HER3 and their corresponding active phosphorylated forms, pEGFR and pHER3, in agreement with previously reported results in lung and head and neck cancer cells and cetuximab-resistant non-small cell lung cancer cells." (PMID 32414394, 2020). "Moreover, epidermal growth factor receptor (EGFR), human EGFR-2, excision repair cross-complementation group 1, ribonucleotide reductase M1, and breast cancer gene (BRCA have been proposed as prognostic and predictive biomarkers in early-stage non-small-cell lung cancer (NSCLC)." (PMID 31450665, 2019). "Though T790M gatekeeper mutations in EGFR and KRAS mutations define resistance in a majority of non-small cell lung carcinoma (NSCLC) and colorectal cancer patients respectively, these mutations contribute minimally to resistance in HNSCC patients." (PMID 31827134, 2019). "Here we demonstrate that in non-small cell lung carcinoma (NSCLC) cells, PGE2 induces EGFR nuclear translocation via different dynamin-dependent endocytic pathways, promotes the formation of an EGFR-STAT3 complex, affects nuclear EGFR target gene expression and mediates tumor cell proliferation." (PMID 29599917, 2018). "The current study aimed to evaluate the impact of de novo liver metastasis (DLM) on stage IV non-small cell lung cancer (NSCLC) outcomes and to examine whether tyrosine kinase inhibitors (TKI) reverse poor prognosis in patients with DLM and epidermal growth factor receptor (EGFR)-mutant NSCLC." (PMID 28591157, 2017). "Thus, we compared the EGFR mutation status of LN samples obtained by EBUS-TBNA and PTs to estimate the efficacy of using EBUS-TBNA specimens for EGFR testing in advanced, non-squamous, non-small cell lung cancer (NSCLC)." (PMID 27685950, 2016). "The data for dacomitinib, a second-generation EGFR-TKI, treating patients with advanced non-small cell lung cancer (NSCLC) and brain metastasis was lacking." (PMID 40349136, 2025). "First-line treatment for patients with metastatic or recurrent non-small cell lung cancer (NSCLC), with no epidermal growth factor receptor (EGFR) or anaplastic lymphoma kinase (ALK) genomic tumor aberrations." (PMID 35037899, 2022). "Despite that most of the mechanisms of acquired EGFR TKI resistance have been revealed, about 30% of non-small-cell lung cancer (NSCLC) cases have not been fully elucidated, especially for lung adenocarcinoma (LUAD)." (PMID 35399731, 2022). "Recently, it was determined that the EGFR (Epidermal Growth Factor Receptor)-mutant and EGFR-tyrosine kinase inhibitors resistant NSCLC (non-small cell lung cancer) cells, but not normal human lung fibroblasts, are sensitive to lysine deprivation." (PMID 34832852, 2021). "Pretherapeutic cancer samples of 122 patients [86 non-small cell lung cancer and 36 small cell lung cancer (SCLC)] harboring no EGFR/ALK alterations were collected." (PMID 34604048, 2021).
non-small cell lung carcinoma (continued). "However, unlike tyrosine kinase mutations occurring predominantly in non-small cell lung cancer (NSCLC), there is no known correlation between EGFR related biomarkers or specific activating mutations within the EGFR that could predict EGFR inhibitor efficacy in SCCHN." (PMID 34298761, 2021). "Unlike lapatinib, the pan-ErbB inhibitor dacomitinib which has recently been FDA approved for non-small cell lung cancer, prevented HER2 protein synthesis, membrane localisation and eventual EGFR/HER2 heterodimerisation without compromising membrane integrity." (PMID 31209328, 2019). "Of note, AG1478 is an early developed EGFR TKI that is not as specific and potent as the TKIs currently approved for treating non-small cell lung cancer patients, such as gefitinib and erlotinib." (PMID 27074568, 2016). "Epidermal growth factor receptor tyrosine-kinase inhibitors (EGFR-TKI) are a therapeutic option as second-line therapy in non-small-cell lung carcinoma (NSCLC), regardless of the EGFR gene status." (PMID 24408092, 2014). "Two non-small cell lung cancer (NSCLC) cell lines HCC827 and NCI-H460 (H460) were selected for the experiments; HCC827 is a typical EGFR addicted cancer cell line, and H460 is not EGFR addicted, which is for comparison." (PMID 22194952, 2011). "Conversely, while gefitinib, an inhibitor of epidermal growth factor receptor (EGFR) typrosine kianse, improved the objective response rate in non-small cell lung cancer patients, it did not produce survival benefits." (PMID 18205918, 2008). "In addition, unlike the kinase domain alterations seen in non-small-cell lung carcinoma (NSCLC), EGFR alterations in GB lie primarily in the extracellular domain." (PMID 34209513, 2021). "CI: confidence interval; ECOG: eastern cooperative oncology group; BC: British Columbia; NSCLC: non-small cell lung cancer; NOS: not otherwise specified; EGFR: epidermal growth factor receptor; RT: radiotherapy; 3DCRT: 3D conformal radiotherapy; IMRT: intensity modulated radiotherapy." (PMID 31696009, 2019). "However, only stages I to III non-small cell lung cancer (NSCLC) patients were enrolled in our study, and most of these patients did not receive EGFR-TKIs." (PMID 29447182, 2018). "Prior to 2016, effective second-line treatment options in non-small cell lung cancer (NSCLC), particularly in patients with adenocarcinoma who are not eligible for epidermal growth factor receptor (EGFR)- or anaplastic lymphoma kinase (ALK)-targeted therapy, were limited." (PMID 30073583, 2018). "As an example of this hypothesis, it is proposed to combine already marketed targeted therapy drugs against VEGFRs, EGFR, CXCR4 and COX2 in an oncology trial for non-small cell lung cancer patients without further treatment options." (PMID 23877481, 2013). "Since i) a correlation between an increased EGFR copy number and gefitinib was proposed in non-small-cell lung cancer (NSCLC) and ii) immunohistochemistry is not a reliable approach for this determination, we decided to evaluate EGFR amplification status in our series by FISH." (PMID 23497641, 2013). "In non-small cell lung carcinoma (NSCLC), Tid1-S, but not Tid1-L, is required for the EGF-stimulated EGFR transportation into mitochondria, potentially leading to enhanced cancer cell migration and invasion." (PMID 34948322, 2021).
breast carcinoma (4,542 papers, 1988 to 2026). "Breast cancer, a leading cause of global mortality, necessitates novel therapies targeting key drivers like the epidermal growth factor receptor (EGFR)." (PMID 41552637, 2026). "This included PD-L1 CAR T-cell activity against PD-L1+ MDA-MB-231 breast cancer cells and EGFR variant III CAR T-cell activity against EGFRvIII+ U87 glioblastoma cell line." (PMID 40163355, 2025). "In the TN breast cancer phenotype, EGFR is highly expressed, which is associated with cancer progression, proliferation, metastasis, and drug resistance, making EGFR a promising pharmacological target." (PMID 40608162, 2025). "EGFR overexpression has been linked to larger tumor sizes and worse clinical outcomes at diagnosis in 15–30% of cases of breast cancer patients." (PMID 39755633, 2025). "As a member of the HER family, EGFR is associated with unfavorable tumor prognosis; its expression is detected in approximately 40% of breast cancers and overexpression can predict a poor response to endocrine therapy among breast cancer patients." (PMID 41026783, 2025). "This study identifies that there is a subset of breast cancer patients with EGFR amplification with co-incident PI3K pathway mutations who are more likely to respond to this combination therapy." (PMID 40501689, 2025). "Human epidermal growth factor receptor 3 (HER3), a member of the epidermal growth factor receptor (EGFR) family, has been associated with poor clinical outcomes and resistance to targeted therapies in various cancers, including breast cancer." (PMID 41198671, 2025). "Increased PCNA expression has been linked to a poor prognosis in breast cancer patients, and EGFR TKI-resistant breast cancer cells show elevated PCNA expression." (PMID 40560045, 2025). "In this context, in silico techniques can clarify the molecular mechanisms by which camptothecin interacts with breast cancer-associated receptors, including EGFR and HER2." (PMID 40136447, 2025). "This integrated analysis offers new perspectives and methodologies for diagnosing and predicting EGFR mutations in patients with breast cancer, demonstrating potential for clinical application." (PMID 41179692, 2025). "One study linked the STC1 glycoprotein to breast cancer metastases via the EGFR pathway and the downstream MAPK/ERK signaling, which ultimately contributes to cell cycle progression." (PMID 41409683, 2025). "Breast cancer develops when abnormal expression of G2/S phase-regulatory proteins including EGFR and Akt signaling causes uncontrolled cell division." (PMID 39858015, 2025). "Human epidermal growth factor receptor (HER) overexpression is a biological signature of breast cancer, as this oncogenic receptor is also implicated with apoptosis avoidance and drug resistance via the coupling with the PI3K/Akt cell-signalling pathway." (PMID 40002469, 2025). "When activated, both hetero and homodimers of HER2 initiate phosphorylation events similar to those of EGFR, activating several signaling pathways implicated in breast cancer progression." (PMID 39780275, 2025). "With regard to the studies involving the anti-NSCLC and anti-breast cancer activity of thiazolyl–pyrazoline hybrids associated with EGFR inhibition, there are promising results." (PMID 40006082, 2025). "We present evidence of a patient subset with EGFR amplification and PI3Kinase pathway mutations in breast cancer which can be synergistically targeted by dual EGFR/PI3K inhibition." (PMID 40501689, 2025). "Consistent with our results, GPX4 dependency of DTP cells induced by targeted TKI has also been found in HER2‐amplified breast cancer, EGFR‐mutated NSCLC, and BRAF‐mutated melanoma." (PMID 39369284, 2025). "Anti-NSCL or anti-breast cancer activity associated with EGFR inhibition has been demonstrated for some of the chalcone derivatives." (PMID 40006082, 2025).